ADAR (adenosine deaminase RNA specific)
Diseases named in the same sentence as ADAR in open-access papers (continued):
Sharing a sentence is not in itself a finding about the gene and the disease.
glioma (19 papers, 2009 to 2025). A benign or malignant brain and spinal cord tumor that arises from glial cells (astrocytes, oligodendrocytes, ependymal cells). "For instance, the gene of RNA-specific adenosine deaminase (ADAR) was used as a reference gene in a glioma study to validate the chromosomal loss or gain." (PMID 19721812, 2009). "Our study revealed RNA editing levels to be higher in control brain samples and it is significantly reduced in glioma samples which correlate with the RNA expression levels of the ADAR enzymes ADARB1 and ADARB2." (PMID 33062411, 2020). "Regulation of ADAR enzymes in gliomas and the differential editing events between the different types of gliomas was queried to understand how the editing enzymes are regulated and how the regulation correlates with editing during glioma progression." (PMID 33062411, 2020). "We found elevated levels of ADAR in glioma samples as compared to control brain samples, although overall editing was lesser in glioma." (PMID 33062411, 2020). "In order to understand the decreasing pattern of A-to-I editing and circular RNA expression in gliomas relative to normal tissues, we checked the RNA expression levels of ADAR (Adenosine Deaminase Acting on Rna) families that are known to generate A-to-I editing." (PMID 35042936, 2022). "This could be because in general, ADAR enzymes are downregulated in glioma leading to reduced editing while the upregulated editing events may be spurious." (PMID 33062411, 2020). "Indeed, it was shown in a previous report that ADAR enzymes are downregulated in glioma and overexpression of the gene leads to tumor suppressive effects." (PMID 33062411, 2020). "However, out of the three ADAR family enzymes, ADAR was found to be expressed in glioma samples which could be the primary source of A-to-I editing in glioma." (PMID 33062411, 2020). "ADARB2 (Adenosine Deaminase Rna Specific B2), also known as ADAR3, known to antagonize ADAR1 and ADAR2 by competing with them also showed some decrease in high-grade gliomas." (PMID 35042936, 2022). "Deletions of the non-enzymatic ADAR, ADAR3, have also been reported in gliomas, suggesting that the ADARs and specific RNA editing events may play context-specific roles." (PMID 35133980, 2022).
dyschromatosis symmetrica hereditaria (18 papers, 2014 to 2025). Acropigmentation of Dohi is a genodermatosis characterized by the presence of hyperpigmented and hypopigmented macules, principally located on the extremities and limbs. "In contrast, mutations of ADAR are associated with the human diseases dyschromatosis symmetrica hereditaria (DSH) and Aicardi–Goutières syndrome (AGS)." (PMID 29084589, 2017). "Aicardi-Goutieres syndrome (AGS; OMIM #225750) and dyschromatosis symmetrica hereditaria (DSH; OMIM #127400) are correlated with the mutations in the ADAR deaminase domain." (PMID 33415135, 2020).
leukemia (18 papers, 2015 to 2026). A malignant (clonal) hematologic disorder, involving hematopoietic stem cells and characterized by the presence of primitive or atypical myeloid or lymphoid cells in the bone marrow and the blood. "Notably, dysregulated ADAR functions and aberrant A-to-I editing are increasingly associated with leukemia pathogenesis and progression, thereby exihibiting novel clinical potentials." (PMID 42267183, 2026). "In this review, we synthesize current knowledge on A-to-I editing and ADAR in normal hematopoiesis and leukemia." (PMID 42267183, 2026). "Our study reveals a pivotal role for a snoRNA-related lncRNA with a previously unknown structure, LNC-SNO49AB, in ADAR-mediated RNA editing and leukemia progression." (PMID 36316318, 2022). "In fact, a related study recently found CML could not be induced in mice following a bone marrow transplant of marrow cells carrying an ADAR deletion suggesting ADAR1 may be essential for leukemia cell survival." (PMID 30197877, 2018).
Autoimmunity (17 papers, 2018 to 2025). The occurrence of an immune reaction against the organism's own cells or tissues. "The ADAR-intact model is exceptional for its paradoxical combination of tolerated MDA5 hyperactivity with autoimmunity resistance." (PMID 39896491, 2025).
prostate carcinoma (15 papers, 2014 to 2026). A carcinoma that arises from epithelial cells of the prostate gland. "Interestingly, a recent study of copy number alterations in 125 localized prostate tumors identified a recurrent amplification of region of chromosome 1q22.3, spanning the ADAR gene, that was significantly associated with early prostate cancer specific mortality." (PMID 25036877, 2014). "Here, we discover the well-known histone lysine methyltransferase enhancer of zeste homologue 2 (EZH2) as an unexplored ADAR interactor and editing regulator in prostate cancer (PCa)." (PMID 41882000, 2026). "For example, in human prostate cancer, the antisense intronic lncRNA PCA3 inactivates the tumor-suppressor gene PRUNE2 at the RNA level through an ADAR-mediated mechanism and promotes malignant cell growth." (PMID 36795564, 2023). "Moreover, ESS2 expression was highly correlated with adenosine deaminase acting on RNA (ADAR), IFN-inducible transmembrane protein (IFITM) 2, and IFITM3 in patients with prostate cancer." (PMID 37524814, 2023).
COVID-19 (14 papers, 2021 to 2026). A disease caused by infection with severe acute respiratory syndrome coronavirus 2. "This study utilized deep sequencing to analyze potential ADAR signatures (A→G mutations) in SARS-CoV-2 genomes retrieved from nasopharyngeal swabs from patients in the early phase of the COVID-19 pandemic." (PMID 35064076, 2022). "Vaccinated individuals could have enhanced immunity against COVID-19, which could also be in part attributed to the higher level of ADAR and RNA editing activity." (PMID 39308856, 2024). "Therefore, our results of RNA editing in response to COVID-19 vaccines showed a consistent role of ADAR-mediated A-to-I RNA editing in modulating the host’s immunity against SARS-CoV-2 infection." (PMID 39308856, 2024). "Differential ADAR expression probably contributed to RNA editing in response to COVID-19 vaccines." (PMID 39308856, 2024). "We have utilized deep sequencing to determine adenosine to guanine (A→G) mutations, signifying ADAR activity, in clinical samples retrieved from 93 severe acute respiratory syndrome coronavirus 2 (SARS-CoV-2)–infected patients in the early phase of the COVID-19 pandemic." (PMID 35064076, 2022). "First, they have not taken into account viral evolution and RNA editing mediated by the ADAR and APOBEC enzymes, which can introduce unexpected variations at target sites and impact upon the performance of COVID-19 diagnostics." (PMID 33741959, 2021). "Consistently, proteomic and metabolomics data from CMs revealed several genes (KNG1, TXNIP, ITIH4, TIMP1, SERPING1/2/3, ITGA1, ADAR, and CLIC5 etc.)and molecules (adenosine and inosine) were related with platelet activation, thus, adding antiplatelet might be a possible therapeutic for COVID-19." (PMID 35903092, 2022).
thyroid cancer (14 papers, 2020 to 2025). "A noteworthy finding is that endogenous-ADAR can address all SNVs within the RET gene associated with thyroid cancer." (PMID 40330550, 2025). "Our detailed experiments depict a novel mechanism which is TRIM47 promoted the development of thyroid carcinoma via ADAR-associated ubiquitination, and GSK-3β mediated phosphorylation on both/either TRIM47 and ADAR was critical for TRIM47 suppression." (PMID 40618019, 2025). "Based on the analysis of our data above, we would like to claim that TRIM47 promotes thyroid tumorigenesis via the downregulation of ADAR, which is consistence with both the thyroid carcinoma tissues and the cultured TC cells." (PMID 40618019, 2025). "Contrastingly, GSK-3β overexpression was able to promote ADAR ubiquitination and further weaken the stability of ADAR in differentiated thyroid carcinoma FTD-133 cells." (PMID 40618019, 2025). "Inhibition of ADAR expression can significantly inhibit the proliferation, invasion and migration of thyroid cancer cells, reflecting the strong carcinogenic effect of ADAR." (PMID 37414093, 2023). "Because of the importance of ADAR expression in many human cancer cell lines, several groups have proposed the use of ADAR inhibitors as a therapy for lung, breast, and thyroid cancers." (PMID 35586115, 2021). "8-azaadenosine has been used as an ADAR inhibitor in multiple studies involving leukemic stem cells and thyroid cancer cell lines." (PMID 35586115, 2021). "For example, ADAR can promote the development of thyroid cancer through RNA editing of CDK13." (PMID 37414093, 2023). "In addition, more studies unveiled that the imbalance of ADAR expression can lead to cancer, amyotrophic lateral sclerosis, and other diseases, but its pathological role and possible clinical application of ADAR in thyroid cancer are largely unknown." (PMID 40618019, 2025). "Furthermore, we overexpressed HA-ADAR and Flag-TRIM47 in human embryonic kidney HEK-295 T cells and also approved the interaction between ADAR and TRIM47 in non-thyroid carcinoma cell lines." (PMID 40618019, 2025). "Further, the enhancement of ADAR-dependent RNA editing activity (especially the ADAR1p150 isoform) was noted to promote EMT, cell proliferation, invasion, migration, and even the evolution of thyroid carcinoma toward a more undifferentiated and aggressive type." (PMID 35955853, 2022).
lung adenocarcinoma (13 papers, 2017 to 2026). A carcinoma that arises from the lung and is characterized by the presence of malignant glandular epithelial cells. "High ADAR expression is linked to shorter overall survival and poor prognosis in lung adenocarcinoma." (PMID 40852728, 2025). "In particular, the upregulation of ADAR, an enzyme that mediates adenosine-to-inosine editing, has been previously linked to an increase in the invasiveness of lung adenocarcinoma cells and associated with splicing regulation." (PMID 38956576, 2024). "Elevated ADAR expression modulates immune infiltration by increasing T cell exhaustion and altering dendritic cell and macrophage levels in lung adenocarcinoma." (PMID 40852728, 2025). "We knocked down ADAR in lung adenocarcinoma cells and sequenced the cDNA with the more accurate R2C2 nanopore sequencing method." (PMID 37398362, 2023). "It has been shown that increased ADAR expression correlates with tumor recurrence in lung adenocarcinoma." (PMID 32410589, 2020). "Notably, knockdown of ADAR in lung adenocarcinoma cells with amplified ADAR leads to decreased migration and invasion." (PMID 32410589, 2020). "In H1975 lung adenocarcinoma (ADC) cell lines, ADAR is not only upregulated but also has been shown to bind to and edit focal adhesion kinase (FAK), increasing both FAK expression and mesenchymal properties of the cells." (PMID 37398362, 2023). "We generated nanopore data with high sequence accuracy of H1975 lung adenocarcinoma cells with and without knockdown of ADAR." (PMID 37398362, 2023).
multiple myeloma (13 papers, 2017 to 2025). "For instance, the overexpression of the ADAR gene in non-small cell lung cancer leads to increase A-to-I RNA editing at the K12 site of NEIL1, resulting in a change from an arginine codon to lysine codon at position 242, which is also observed in myeloma." (PMID 38493171, 2024). "The risk score was also negatively correlated with the expression of immune checkpoints, indicating that ADAR, FASTKD1 and SNRPD3 might interact with the immune microenvironment of multiple myeloma." (PMID 34976013, 2021).
systemic lupus erythematosus (13 papers, 2014 to 2026). An autoimmune multi-organ disease typically associated with vasculopathy and autoantibody production. "Among them, we identified pathogenic or likely pathogenic variants in genes previously associated with monogenic lupus, including a novel C1QA variant as well as other lupus-associated genes (COPA, ADAR, TLR7, IKZF3, RELA, PTPN11, SERPING1)." (PMID 41930824, 2026). "This balance is disrupted by gain-of-function IFIH1 mutations or loss of ADAR activity, triggering spontaneous IFN production in immune disorders, including Aicardi-Goutières syndrome (AGS) and systemic lupus erythematosus (SLE)." (PMID 40773553, 2025). "OAS proteins, particularly OAS1, and the editing enzymes ADAR and APOBEC were found upregulated in Systemic Lupus Erythematosus (SLE)." (PMID 35757716, 2022).
cervical cancer (12 papers, 2017 to 2025). A primary or metastatic malignant neoplasm involving the cervix. "Based on the pattern of ADAR and DDR expression, we classified cervical cancer patients into three clusters, with cluster 3 showing the best survival, confirming the predictive function of ADAR and DDR." (PMID 37735483, 2023). "According to ADAR and DDR levels, a consensus clustering algorithm was performed to stratify the tumor samples of cervical cancer with the k = 3 as the number of clusters." (PMID 37735483, 2023).
liver cancer (12 papers, 2017 to 2025). An epithelial or non-epithelial malignant neoplasm that arises from the liver. "Upregulation and overexpression of the ADAR gene occur in over 8% of breast, lung, and hepatic cancers." (PMID 40618019, 2025). "Amplification and overexpression of the ADAR gene occurs in over 8% of breast, lung, and hepatic cancers." (PMID 32410589, 2020).
amyotrophic lateral sclerosis (10 papers, 2016 to 2025). Amyotrophic lateral sclerosis (ALS) is a neurodegenerative disease characterized by progressive muscular paralysis reflecting degeneration of motor neurons in the primary motor cortex, corticospinal tracts, brainstem and spinal cord. "In addition, the imbalance of ADAR expression can lead to cancer, amyotrophic lateral sclerosis, and other diseases, and the pathological and clinical role of ADAR in TC has not been revealed." (PMID 40618019, 2025). "Supporting important roles in neuron function, dysfunction of ADAR genes has been related to several neurological disorders, including Amyotrophic lateral sclerosis (ALS)." (PMID 32630140, 2020). "Although, anomalies in RNA editing are associated with multiple neurological disorders such as epilepsy, schizophrenia, and amyotrophic lateral sclerosis (ALS; Slotkin and Nishikura, 2013), the molecular determinants of ADAR-mediated pathogenesis still remain elusive." (PMID 27458478, 2016).
Sepsis (9 papers, 2020 to 2026). Sepsis is defined as life-threatening organ dysfunction caused by a dysregulated host response to infection. "Previous studies have shown that ADAR is highly expressed in macrophages and has a protective effect on sepsis." (PMID 35559016, 2022). "Nevertheless, the role of ADAR-mediated A-to-I RNA editing played in sepsis remains unelucidated, especially in SAE." (PMID 35559016, 2022). "ADAR is highly expressed in the small intestine of septic mice, which inhibits inflammation and plays a protective role against sepsis, providing a new potential therapeutic target for sepsis." (PMID 35559016, 2022). "Our results showed that both the levels of ADAR expression and A-to-I RNA editing in the brain decreased in sepsis, which could be in line with a protective role of ADAR and A-to-I RNA editing against sepsis." (PMID 35559016, 2022).
chronic myeloid leukemia (8 papers, 2015 to 2023). "For instance, increased ADAR-mediated RNA editing of stem cell regulatory let-7 miRNAs may enhance leukemic self-renewal and contribute to chronic myeloid leukemia." (PMID 32157211, 2020).
HIV-1 infection (8 papers, 2013 to 2025). The type species of lentivirus and the etiologic agent of acquired immunodeficiency syndrome (AIDS). "It has been shown that ADAR-1 and PKR interact directly during HIV-1 infection." (PMID 33984068, 2021).
ovarian carcinoma (8 papers, 2016 to 2025). A malignant neoplasm originating from the surface ovarian epithelium. "Based on evidence of altered ADAR expression in epithelial ovarian cancers (EOC), we hypothesized that single nucleotide polymorphisms (SNPs) in ADAR genes modify EOC susceptibility, potentially by altering ovarian tissue gene expression." (PMID 27911851, 2016). "ADAR expression levels have been found to be significantly greater in peritoneal fluid obtained from patients with epithelial ovarian cancer compared to patients with benign disease." (PMID 29262670, 2017). "In 2016, Permuth and colleagues suggested that RNA editing, which is a post-transcriptional modification where adenosine is converted to inosine by a family of enzymes known as adenosine deaminases acting on RNA (ADAR), may have a role in epithelial ovarian cancers." (PMID 29262670, 2017).
Alzheimer disease (7 papers, 2018 to 2025). A progressive, neurodegenerative disease characterized by loss of function and death of nerve cells in several areas of the brain leading to loss of cognitive function such as memory and language. "Interestingly, ADAR enzymes are involved in regulation of aging processes, and alterations in A-to-I editing in the brain were observed in aging and in Alzheimer’s disease patient populations." (PMID 29310578, 2018). "For example, we found that levels of ADAR, XRCC6 and SBDS were reduced in 5 of 7 Alzheimer’s disease samples and levels of DDX5, U2AF2, ILF3 were reduced in 4 of 7 Alzheimer’s disease NPC vasculature samples by greater than 50%." (PMID 36196083, 2022). "However, many of the RBPs under-expressed in Alzheimer’s disease HPC vasculature do play important roles in neurological health and neurodegenerative diseases including ADAR, XRCC6, U2AF2 and ILF3." (PMID 36196083, 2022).
Encephalopathy (7 papers, 2020 to 2026). Encephalopathy is a term that means brain disease, damage, or malfunction. "Whole-exome sequencing identified a homozygous pathogenic ADAR frameshift variant (NM_001111.5:c.2433_2434del) and a homozygous likely pathogenic TSHB variant (NM_000549.5:c.313T >C; p.Cys105Arg), confirming combined ADAR-related encephalopathy and isolated C-CH." (PMID 42256321, 2026).
astrocytoma (6 papers, 2009 to 2026). "In order to identify which ADAR (ADAR1 and/or ADAR2) was responsible for the editing events found in the OPHN1 transcript, we took advantage of the astrocytoma cell lines (U118 and U87) available in our laboratory, in which we stably modulate the expression of the ADAR enzymes." (PMID 24637888, 2014). "In addition, despite our small cohort of tumors samples, we observed that a correlation exists between a decrease in ADAR-mediated RNA editing on BLCAP transcript and the histological grade of malignancy in pediatric astrocytomas." (PMID 19908260, 2010).